Y_RNA (Y RNA )
Gene: Miscellaneous RNA gene on chromosome 7 (140,609,847 to 140,609,955, forward strand). Ensembl gene ENSG00000201354.
Homologues: Orthologues: chimpanzee Y_RNA (99% identical), macaque Y_RNA (92% identical). Paralogues in human: Y_RNA (83% identical), Y_RNA (82% identical), Y_RNA (81% identical), RNY1P5 (80% identical), Y_RNA (79% identical), RNY1 (78% identical), Y_RNA (78% identical), RNY1P1 (77% identical), Y_RNA (77% identical), Y_RNA (76% identical), RNY1P2 (75% identical), Y_RNA (75% identical), and 91 more.